CCR4 (C-C motif chemokine receptor 4)
Description:
High affinity receptor for the C-C type chemokines CCL17/TARC, CCL22/MDC and CKLF isoform 1/CKLF1. The activity of this receptor is mediated by G(i) proteins which activate a phosphatidylinositol-calcium second messenger system. Can function as a chemoattractant homing receptor on circulating memory lymphocytes and as a coreceptor for some primary HIV-2 isolates. In the CNS, could mediate hippocampal-neuron survival.
Synonyms: CC-CKR-4; CD194; CMKBR4; CKR4; k5-5; ChemR13; HGCN:14099
Tractability: Small molecule: a high-quality ligand is known; it belongs to a druggable protein family. Antibody: an approved drug acts on it; its Gene Ontology location is reachable by antibodies, with high confidence; UniProt places it where antibodies can reach, with medium confidence; UniProt predicts a signal peptide or a membrane-spanning region; the Human Protein Atlas places it where antibodies can reach. PROTAC: a small molecule that binds it is known.
Target class: Chemokine receptor; Peptide receptor (family A GPCR); Family A G protein-coupled receptor; CC chemokine receptor; Membrane receptor
Gene: Protein-coding gene on chromosome 3 (32,951,644 to 32,957,120, forward strand). Ensembl gene ENSG00000183813.
Subcellular location: Cell membrane
Subcellular location (Human Protein Atlas): Plasma membrane
Pathways (Reactome):
Signal Transduction: Chemokine receptors bind chemokines; G alpha (i) signalling events
Gene Ontology:
Molecular function: C-C chemokine receptor activity; protein binding; C-C chemokine binding; chemokine receptor activity; G protein-coupled receptor activity
Biological process: calcium-mediated signaling; cell chemotaxis; chemotaxis; immune response; inflammatory response; positive regulation of cytosolic calcium ion concentration; cellular response to cytokine stimulus; chemokine-mediated signaling pathway; G protein-coupled receptor signaling pathway
Cellular component: plasma membrane; external side of plasma membrane; membrane
Genetic constraint (gnomAD): Loss-of-function variants: 11 observed, 22.52 expected, observed/expected ratio (o/e) 0.49, 90% interval 0.31 to 0.81. The upper end of that interval is the gene's LOEUF score, 0.81, which puts it in group 3 of 6, group 1 being the genes least tolerant of losing a copy. Missense variants: 385 observed, 456.9 expected, observed/expected ratio (o/e) 0.84, 90% interval 0.77 to 0.92. Synonymous variants: 217 observed, 185.13 expected, observed/expected ratio (o/e) 1.17, 90% interval 1.05 to 1.31.
Homologues: Orthologues: chimpanzee CCR4 (100% identical), macaque CCR4 (99% identical), pig CCR4 (93% identical), dog CCR4 (92% identical), guinea pig CCR4 (89% identical), rat Ccr4 (88% identical), mouse Ccr4 (87% identical), zebrafish ccr8.1 (41% identical), zebrafish cabz01093075.1 (39% identical), zebrafish si:ch211-207g17.3 (38% identical), zebrafish si:cabz01093077.1 (37% identical), zebrafish ccr2 (36% identical), and 1 more. Paralogues in human: CCR5 (47% identical), CCR1 (46% identical), CCR2 (45% identical), CCR3 (43% identical), CCR8 (42% identical), CX3CR1 (40% identical), ACKR2 (38% identical), CCR6 (35% identical), CXCR2 (34% identical), CCR7 (33% identical), CXCR1 (33% identical), CCR9 (32% identical), and 11 more.
Diseases named in the same sentence as CCR4 in open-access papers:
CCR4 is named in the same sentence as 282 diseases in open-access papers, as found by Europe PMC text mining. Sharing a sentence is not in itself a finding about the gene and the disease. The quoted sentences say what the papers report.
lymphoma (57 papers, 2011 to 2026). A malignant (clonal) proliferation of B- lymphocytes or T- lymphocytes which involves the lymph nodes, bone marrow and/or extranodal sites. "Mogamulizumab was approved in Japan in March 2012 for the treatment of relapsed or refractory CCR4-positive adult T-cell leukemia/lymphoma, which is also caused by HTLV-1." (PMID 38430272, 2024). "Gene CCR4 was reported to be associated with adult T-cell leukaemia and lymphoma in the COSMIC database." (PMID 32429941, 2020). "In this article, we will focus our attention upon CC Chemokine Receptor Four (CCR4) which has been implicated in diseases as diverse as allergic asthma and lymphoma." (PMID 25981299, 2015). "Additionally, because of mutations in GATA3, CCR4 is also expressed in lymphoma cells, which leads to the further recruitment of malignant cells." (PMID 32731404, 2020). "Other notable agents include CCX872, a CCR2 antagonist for pancreatic cancer, and mogamulizumab (KW‐0761), an anti‐CCR4 mAb, which is in phase II trials for adult T‐cell leukemia/lymphoma." (PMID 40969301, 2025). "Ranging from well-established B-cell targets such as CD20 and CD19 to targets including CD52 and CCR4 in T-cell malignancies, mAbs continue to expand the treatment landscape in lymphomas." (PMID 39456582, 2024). "Monoclonal antibodies targeting CCR4, such as mogamulizumab, have been approved in Japan for the treatment of adult T‐cell leukemia‐lymphoma." (PMID 39508721, 2024). "Mogamulizumab (MOG), a humanized monoclonal anti-CCR4 antibody, exerts strong antibody-dependent cellular cytotoxic effects on CCR4-positive adult T-cell leukemia/lymphoma (ATLL) cells." (PMID 36083572, 2023). "Mogamulizumab is another anti-chemokine/anti-CCR4 antibody that targets lymphomas as well, and has been clinically approved for Cutaneous T-cell lymphomas and Adult T-cell leukemia/lymphoma." (PMID 37575219, 2023). "Mogamulizumab became the first anti-CCR4 biologic approved in 2012 when Japan approved it for the treatment of relapsed or refractory CCR4+ adult T cell Leukemia-Lymphoma (ATLL)." (PMID 38022633, 2023). "CCR4 is an interesting target blocked by the drug Mogamulizumab which was launched in 2012 for CCR4‐positive adult T‐cell leukaemia‐lymphoma." (PMID 37186423, 2023). "This mAb was originally approved for the treatment of chemokine C receptor 4 (CCR4)‐expressing T‐cell leukemia–lymphoma and peripheral T‐cell lymphoma." (PMID 35182428, 2022). "This clone was confirmed to have no competitive inhibition with KM2760 against the adult T-cell leukemia/lymphoma cell line MT-4, which is known to express CCR4." (PMID 36522365, 2022). "Since CCR4- effector T cells are barely present at the tumor site, the forced co-expression of surface CCR4 in CAR-T cells appears to be a promising therapeutic strategy in the treatment of certain types of lymphomas." (PMID 35211124, 2022). "It has been evaluated in humans for the treatment of CCR4+ adult T cell leukemia/lymphoma that has relapsed or become refractory." (PMID 35222362, 2022). "Mogamulizumab targets extracellular N‐terminal domain of CCR4, which is expressed in most adult T‐cell leukemia/lymphoma (ATL) cases." (PMID 33022137, 2021). "The CCR4-CCL22/CCL17 interaction plays a major role in Treg migration and metastasis of CCR4-positive lymphoma cells." (PMID 33628584, 2021). "In this regard, mogamulizumab, an anti-CCR4 monoclonal antibody, was recently developed for the treatment of CCR4-expressing adult T-cell leukemia/lymphoma." (PMID 34885241, 2021). "Mogamulizumab is a monoclonal antibody against CCR4 that was designed in Japan and licensed for the management of relapsed or refractory adult T cell leukemia/lymphoma in 2012 and elapsed/refractory CCR4+ cutaneous T cell lymphoma in 2014." (PMID 32731404, 2020). "A clinical trial of CD30-directed CAR-T cells co-expressing CCR4 in patients with relapsed/refractory CD30+ lymphomas is planned to open in the near future." (PMID 30841880, 2019).
lymphoma (continued). "Clinical trials have been conducted for treatment with chemokines, such as the use of monoclonal antibodies against CCR4 in the treatment of lymphoma, and a significant anti-tumor effect has been observed." (PMID 30477520, 2018). "Another recent report described a case of post-transplant adult T-cell leukemia/lymphoma in whom CXCR3+CCR4+ T cells were observed." (PMID 26795118, 2016). "Depletion of circulating CCR4+ eTregs by an anti-CCR4 mAb restored antigen-specific CTL responses in an adult T-cell leukemia-lymphoma patient." (PMID 27509527, 2016). "Despite great expectations, so far, only one anti-chemokine receptor antibody has been approved for its clinical use, mogamulizumab, an anti-CCR4 antibody, granted in Japan to treat refractory adult T-cell leukemia and lymphoma." (PMID 25688243, 2015). "Interestingly, the defucosylated anti‐CCR4 antibody mogamulizumab is approved for use in cutaneous T‐cell lymphoma and adult T‐cell leukemia/lymphoma, where it facilitates the removal of tumor cells through enhanced ADCC." (PMID 40969301, 2025). "Moreover, CAR-T therapy emerges as a highly specific and selective armamentarium against T lymphomas expressing CCR4, with promising results that need to be confirmed using in vivo studies." (PMID 38804300, 2024). "Mogamulizumab was subsequently approved for relapsed or refractory CCR4-positive peripheral T-cell lymphoma, relapsed or refractory cutaneous T-cell lymphoma, and chemotherapy-untreated CCR4-positive adult T-cell leukemia/lymphoma, combined with other antineoplastics." (PMID 38430272, 2024). "For example, the PTCL-GATA3 subtype may benefit from a chimeric anti-CCR4 monoclonal antibody that is effective against adult T-cell leukemia/lymphoma." (PMID 36466894, 2022). "CCR4 could be used as a therapeutic target for cancer immunotherapy of several cancers, such as adult T-cell leukemia/lymphoma and cutaneous T-cell lymphomas." (PMID 35619698, 2022). "In addition, CCR4 expression by MJ, a FoxP3-expressing adult T cell leukemia/lymphoma (ATLL) cell line, which highly expresses CCR427, was reduced by RNA interference-mediated knockdown of FoxP3 gene." (PMID 34907192, 2021). "Mogamulizumab (KW-0761) is a defucosylated, humanized, IgG1 monoclonal antibody directed against CCR4 that has direct cytotoxic effect on CCR4-positive lymphoma cells via ADCC, as well as immunomodulatory potential by depletion of regulatory T cells to enhance anti-tumor immunity." (PMID 32448357, 2020). "Mogamulizumab (KW-0761), a defucosylated, humanized monoclonal antibody targeting CCR4, has direct cytotoxic effect on CCR4-positive lymphoma cells via antibody-dependent cellular cytotoxicity, as well as immunomodulatory potential by depletion of regulatory T cells to enhance anti-tumor immunity." (PMID 33292562, 2020). "In addition to CCR2 expression, the transgenic coexpression of CCR4 improved the homing of CD30 CAR-T cells to CD30+ HL that secreted CCL17 (the ligand for CCR4) and thereby improved the anti-lymphoma effects." (PMID 31637014, 2019). "Interestingly, treatment of these mice with a therapeutic humanized anti-CCR4 Ab (mogamulizumab) suppressed the growth of a CCR4+ lymphoma, suggesting that the human NK cells in the mice exerted active Ab-dependent cellular cytotoxicity in vivo." (PMID 28405194, 2017). "Indeed, a nonfucosylated humanized anti-CC chemokine receptor 4 (CCR4) antibody, mogamulizumab, was approved in Japan in 2012 to treat relapsed/refractory CCR4-positive adult T-cell leukemia-lymphoma." (PMID 26444434, 2015). "Recently, the C–C chemokine receptor 4 (CCR4) targeting glyco-engineered antibody mogamulizumab has been approved in Japan for use in patients with relapsed and refractory CCR4-positive adult T cell leukemia/lymphoma (ATL)." (PMID 23543707, 2013).
lymphoma (continued). "Additionally, the anti-CC chemokine receptor 4 (CCR4) antibody KW-0761 is undergoing a phase II clinical trial to assess efficacy, safety, and pharmacokinetic profiles in CCR4-positive adult T-cell leukemia/lymphoma." (PMID 38468825, 2024). "Moreover, an immunosuppressive tumor microenvironment, with tons of interleukin 6 (IL-6), IL-10, EBV-encoded microRNAs, and C-C motif chemokine receptor 4 (CCR-4)+ regulatory T-cells (Treg), may aid lymphoma cell survival in immunocompetent individuals." (PMID 33564306, 2021). "Hence, CCR4 represents an ideal target to block both Tregs and CCR4-positive lymphoma cells." (PMID 33628584, 2021). "Indeed, a phase I trial of a defucosylated humanized anti-CC chemokine receptor 4 (CCR4) antibody, KW-0761, in relapsed CCR4-positive adult T-cell leukemia–lymphoma or other peripheral T-cell lymphomas revealed that the antibody had antilymphoma activity even at a low dose of 0.01 mg/kg." (PMID 22023369, 2011). "Upregulated expression of CCR4 for CCL5, CCR6 for CCL18, and CCR7 for CCL19 was observed in lymph nodes, where lymphocytes were replaced by lymphoma cells." (PMID 39894788, 2025). "RNA sequencing revealed upregulated expression of chemokine genes, including CCL5, CCL18, and CCL19, in WDL and that of the corresponding chemokine receptor genes CCR4, CCR6, and CCR7 in the lymphoma cells." (PMID 39894788, 2025). "Due to its role in malignant lymphocyte chemotaxis, CCR4 is expressed in MF (including CD8+ subtypes), SS, and other lymphomas, such as T-cell leukaemia/lymphoma (ATLL)." (PMID 38804300, 2024). "Of note, CCR4, the receptor of TARC/CCL17 and CCL21, was also among the genes significantly downregulated in HLA‐I+ lymphomas." (PMID 38836098, 2024). "The mogamulizumab treatment was also shown to efficiently deplete CCR4-expressing Treg cells and to increase the number of tumor-specific CD8+ T cells in the blood of patients with adult T-cell leukemia/lymphoma." (PMID 34885241, 2021). "Lymphoma cells in all 11 ATLL patients were CD3+, CD25+, and of those, nine (100%) were CD194+ (CCR4) and nine (82%) were CD4+." (PMID 33087157, 2020). "It was first approved in Japan in 2012 for relapsed or refractory CCR4+ adult T-cell leukemia-lymphoma (ATL), and approval for first-line treatment of CCR4+ ATL was granted in 2014." (PMID 31801624, 2019). "The expression of chemokine receptors, CCR4 for CCL5, CCR6 for CCL18, and CCR7 for CCL19, was upregulated in lymph nodes with conspicuous lymphoma infiltration, likely representing their expression in lymphoma cells." (PMID 39894788, 2025). "Additionally, Treg infiltration, dependent on CCR4 and CCR5, has been reported in breast cancer, lymphoma, squamous cell carcinoma, and PDAC." (PMID 39143228, 2025). "Since EBV+ lymphomas secrete high quantities of CCL3, CCL4, CCL22, and CXCL10 compared to EBV- lymphoma lines, the high expression of CCR5, CCR4, and CXCR3 on both EBV VST groups may indicate complementary/alternate axes of migratory mechanisms." (PMID 39011042, 2024). "Histology showed a lymphoid infiltrate with a negative fungal stain, so a presumptive diagnosis of lymphoma infiltration was made, and the patient started the CCR-4 antagonist Mogamulizumab treatment in August 2022." (PMID 39194909, 2024). "As anti-CD30 CAR T-cells expressing CCR4 lead to improved tumor honing and anti-lymphoma activity when compared with anti-CD30 CAR T-cells lacking CCR4, this approach is now being studied in a clinical trial of patients with R/R CD30+ cHL and CTCL." (PMID 39456582, 2024). "Furthermore, data show a majority of adult T cell leukaemia/lymphoma cells which share the Treg phenotype, CD4+CD25+CCR4+FOXP3+, leading to the suggestion that adult T cell leukaemia/lymphoma cells are descendants of Tregs." (PMID 36794233, 2022). "As in the other lymphoma entities, the CCR1 and CCR4 expression was rarely or weakly detectable." (PMID 35887224, 2022).
lymphoma (continued). "Furthermore, our observation that selected GATA-3 target genes, including c-Myc, CCR4, IKZF3 and ITK, are therapeutically targetable is noteworthy, as improved therapeutic strategies for these lymphomas are clearly needed." (PMID 36329027, 2022). "To investigate whether the dissemination of lymphoma cells is dependent on the expression of chemokine receptors, we examined the expression of the chemokine receptors CXCR3, CCR4, CCR5 and CCR1 in primary cases of ALCL and cHL by immunohistochemistry." (PMID 31581676, 2019). "They found that CD30-directed CAR-T cells that expressed CCR4 had improved migration to the tumor and increased anti-lymphoma activity compared to CD30-directed CAR-T cells that did not express CCR4 in HL mouse models." (PMID 30841880, 2019). "In this article, we will focus upon the chemokine CCR4 and its ligands CCL17 and CCL22, which are postulated to play key roles in the pathogenesis of allergic asthma, atopic dermatitis and a variety of cancers, including breast cancer, gastric cancer renal cell cancer and lymphoma." (PMID 25981299, 2015). "Savoldo’s group showed that CD30 CAR-T cells co-expressing CCR4 (CCR4.CD30.CAR-T cells) exhibited improved tumor homing and anti-lymphoma activity compared to CD30 CAR-T cells lacking CCR4 expression." (PMID 39134804, 2024). "CCR4 is preferentially expressed on TI-Treg cells rather than on Teff cells, with the CCL17/22-CCR4 axis playing an important role in lymphomas and in breast, lung, ovarian, gastric, and prostate cancers." (PMID 29463952, 2017). "In another study CD30.CAR‐Ts co‐expressing the cognate receptor for CCL17, CCR4 (CCR4.CD30.CAR‐Ts) with improved tumor homing and anti‐lymphoma activity compared with CD30.CAR‐Ts not expressing CCR4 were used to treat 8 R/R cHL patients, with 6 (75%) achieving a CR and 2 (25%) a PR." (PMID 41123243, 2026).